BRAP (BRCA1 associated protein)
Diseases named in the same sentence as BRAP in open-access papers (continued):
Sharing a sentence is not in itself a finding about the gene and the disease.
cancer (4 papers, 2019 to 2022). A tumor composed of atypical neoplastic, often pleomorphic cells that invade other tissues. "Our data indicate that the combination of NF1 mutation and PTPN11 mutation drives the malignancy of NF1 cells and that SHP-2 inhibition by BRAP is a potential therapeutic strategy for NF1-associated malignant tumors." (PMID 35625983, 2022). "For example, in human pan-cancer studies, overexpression of BRCA1-associated protein (BRAP) was associated with poor prognosis and immune infiltration in a variety of cancers." (PMID 35677427, 2022). "In the present study, we comprehensively analyzed the association between BRAP expression and patients’ prognosis in 33 cancer types." (PMID 33240929, 2020). "We detected 14 heterozygous variants within the coding regions of 13 cancer- and other disease-related genes, including single-base substitutions in the PTPN11 (c.1508G > T, p.Gly503Val) and BRAP (c.1109G > C, p.Gly370Ala) genes." (PMID 35625983, 2022). "Our findings revealed the possible role of BRAP across cancers, suggesting that BRAP is a potential prognostic biomarker and is correlated with immune infiltration in many cancers, especially in LIHC." (PMID 33240929, 2020). "By univariate survival analysis of 33 cancer types, we found that BRAP expression impacted patients’ OS in 6 cancer types, including KICH, KIRC, KIRP, LIHC, MESO, and THYM." (PMID 33240929, 2020). "Forest plot revealed that BRAP expression impacted patients’ PFI in two cancer types, including ACC and LIHC." (PMID 33240929, 2020). "BRAP expression in human pan-cancer was analyzed via the Genotype-Tissue Expression (GTEx) and The Cancer Genome Atlas (TCGA) database." (PMID 33240929, 2020). "In this study, we analyzed the correlation between BRAP levels and prognosis of patients in human pan-cancer." (PMID 33240929, 2020). "We found that BRAP was abnormally overexpressed in 25 types of cancer and significantly correlated with MMR and DNA methylation." (PMID 33240929, 2020). "Considering the small number of normal samples in TCGA, we integrated the GTEx database and TCGA database to analyze the expression difference of BRAP in 27 cancer types." (PMID 33240929, 2020). "BRAP is abnormally overexpressed and significantly correlated with MMR gene mutation level and DNA methyltransferase expression in human pan-cancer." (PMID 33240929, 2020). "Our last study showed that BRAP amplification occurs in many types of human cancer." (PMID 33240929, 2020). "Furthermore, we analyzed the correlation of BRAP expression with patients’ DFI and found that BRAP expression impacted patients’ DFI in three cancer types, including KIRP, LIHC, and PRAD." (PMID 33240929, 2020). "These previous studies all indicate that BRAP may be aberrantly expressed in various cancers and play important roles in cancer carcinogenesis and progression." (PMID 33240929, 2020). "In summary, there results indicate that BRAP may mediate tumorigenesis by regulating DNA damage or methylation status in human pan-cancer." (PMID 33240929, 2020). "Overall, these results indicate that BRAP expression was strongly correlated with patients’ prognosis in many cancers, especially in LIHC, whether OS, DFI, or PFI." (PMID 33240929, 2020). "Furthermore, we observed that BRAP expression was positively correlated with immune infiltration and immune checkpoint markers in various types of cancer, especially in LIHC." (PMID 33240929, 2020).
cancer (continued). "We next investigated whether BRAP expression was correlated with the prognosis of patients in pan-cancer patients." (PMID 33240929, 2020). "BRAP expression is increased in human pan-cancer samples compared with normal tissues." (PMID 33240929, 2020). "In this study, we first comprehensively analyzed BRAP in human pan-cancer." (PMID 33240929, 2020). "Therefore, we studied whether BRAP expression was correlated with the level of immune infiltration in 33 cancer types from the TIMER database." (PMID 33240929, 2020). "Interestingly, BRAP expression was strongly correlated with DNMT1, DNMT2, DNMT3A, and DNMT3B expression in human pan-cancer, and UCS, TGCT, and SARC were exceptions." (PMID 33240929, 2020). "Although the function of BRAP in ESCC is very clear, its roles in human pan-cancer are still largely unknown." (PMID 33240929, 2020). "Although BRAP has been extensively studied in ESCC, its roles in pan-cancer and whether it can be used as a biomarker are still unknown." (PMID 33240929, 2020).
BRAP also shares sentences with these, for which no sentence is quoted: alcohol dependence (2 papers); breast carcinoma (2); cardiovascular diseases (2); carotid atherosclerosis (2); coronary artery disease (2); arteriosclerosis (1); cervical cancer (1); cutaneous melanoma (1); gout (1); heart failure (1); liver disease (1); lung carcinoma (1); primitive neuroectodermal tumor (1); pulmonary arterial hypertension (1); soft tissue sarcoma (1); thrombocythaemia (1); type 2 diabetes (1); type I diabetes (1).